IL6 (interleukin 6)
Diseases named in the same sentence as IL6 in open-access papers (continued):
Sharing a sentence is not in itself a finding about the gene and the disease.
influenza (continued). "After influenza infection, IFN-α/β, IFN-α, and IL-2 appear to have protective roles against influenza infection, while IL-1, TNF-α, and IL-6 seem to be involved in the inflammatory phase of the infection." (PMID 33374214, 2020). "IL-6 and CRP were the synthesis of pro-inflammatory cytokines released from the epithelial cells invaded by influenza and resulted in further alveolar damage according to enhance phagocytosis of immune cells and activate a series of innate immunoresponses." (PMID 33537328, 2020). "In contrast, human PBMC cultured with influenza vaccine and inflammatory cytokines (IL-1, IL-6 and TNF) showed a suppressed T cell response to a subsequent influenza challenge." (PMID 32399058, 2020). "Treatment with exogenous SP-A decreases influenza infection and the production of inflammatory cytokines including TNF-α, IL-6 and IFN-γ." (PMID 33542724, 2020). "Our data also showed rapidly increased secretion of IL-6 and CRP in severe influenza patients with aspergillosis than those with influenza alone." (PMID 33537328, 2020). "Serum concentration of IL-6, IL-1β, TNFα, IFNγ were found elevated in cases of HAdV, RSV, and influenza AURTIs compared to age-specific normal values." (PMID 33066100, 2020). "In alveolar A549 cells, influenza infection increased the production of pro-inflammatory cytokines and chemokines and the addition of vitamin D either before or after influenza infection reduced gene expression of among other cytokines TNF alpha and IL-6." (PMID 32922301, 2020). "Elevated IL-6 levels are also observed in SARS-CoV-2 infections, severe influenza, rhinovirus, RSV infection, as well as in similar respiratory infections." (PMID 33071786, 2020). "Accordingly, our study has shown that rosiglitazone treatment decreased the levels of IL-6, IL-12, CCL-2 and CCL6 during influenza infection." (PMID 31159430, 2019). "This pro-inflammatory role of p38 has also been demonstrated in vivo, as treatment of influenza-infected BALB/c mice with SB203580 lowered the concentration of TNF-α, IL-1β and IL-6 protein in lung homogenates." (PMID 30764493, 2019). "The previous study demonstrated that high levels of IL-6 and IFN-γ were detected in naive mouse lungs after infection, whereas little or no proinflammatory cytokines were present in the lungs of the influenza HA VLP-immunized mice." (PMID 31246961, 2019). "On the other hand, Eotaxin, MIG, IL-6 and TNF-α, which are pro-inflammatory and chemoattractant responses that are induced by influenza infection, peaked early in the vaccinated group at 3 days post infection but then declined by 7 days post infection." (PMID 29267331, 2017). "However, whether IL-6 impacts lung repair in influenza pathogenesis remains unclear." (PMID 28262742, 2017). "FP7 led to a significant reduction in influenza-induced gene expression for TNF-α, IL-1β, IFN-β, KC (P < 0.01), IL-6, and RANTES (P < 0.05)." (PMID 28106157, 2017). "Given elevated expression of TGF-β in the BAL fluid of the infected IL-6−/− mice, we further detected the typical EMT marker α-SMA to assess the potential involvement of IL-6 in the regulation of EMT during influenza infection." (PMID 28262742, 2017). "Specifically, monocytes (macrophage precursors) obtained from older adults prior to influenza vaccination exhibit impaired function with decreased TNF-α and IL-6 secretion, but intact IL-10 responses." (PMID 28769922, 2017). "Here, we describe the immunogenicity and safety of influenza vaccination and long term seroprotection on a pediatric cohort diagnosed with JIA receiving immunomodulatory therapy including anti IL-6 and anti IL-1R therapy and review the published literature." (PMID 28784185, 2017). "In a small cohort of critically ill children and young adults, we previously reported associations between high levels of individual cytokines circulating in the bloodstream (IL6, IL8, IP10, GMCSF, MCP1, and MIP1α) with fatal influenza infection." (PMID 29163498, 2017).
influenza (continued). "Specifically, it has been shown that pDC stimulation with enveloped viruses, such as herpes simplex or influenza, results in the production of the inflammatory cytokines TNF-α and IL-6, as well as ß chemokines such as MIP-1α and MIP-1ß." (PMID 26871575, 2016). "In this current study, we examined the effects of IL-2 and IL-6 on the CD8+ T cell response to influenza virus and showed that the addition of these cytokines restored the response to influenza in aged mice to that observed in young mice." (PMID 27322555, 2016). "We found that in H1N1-inoculated mice, anti-HMGB1 mAb significantly suppressed the local production of IL-6 and TNF-α, key cytokines orchestrating the pathophysiology of highly virulent influenza strains." (PMID 26067826, 2015). "• Blocking TNF-α markedly inhibited the burst of major inflammatory cytokines (for example, IL-6, IFN-γ, and TNF-α) in the lung tissue of influenza-infected mice." (PMID 24373231, 2013). "The antiinfluenza properties of IL-6, TNF-α, and IFN-γ have been discussed in many studies, despite their participation in cytokine storms triggered by influenza infection." (PMID 24159339, 2013). "The mouse adapted influenza strain, PR8, also elicited greater production of IFN-β in P3C-primed cells as well as diminished production of IL-6 mRNA." (PMID 23853595, 2013). "We selected three important inflammatory cytokines (TNF-α, IL-6, and IFN-γ) to evaluate the cytokine burst in lethally influenza-infected mice." (PMID 24373231, 2013). "Overall, our results support the notion of IL-6, IFNγ and perhaps MCP-1 as potential indicators for more severe influenza disease." (PMID 22808082, 2012). "Elevated plasma levels of IL-6, IL-12 and IFN-γ in patients with severe influenza were recently reported." (PMID 21966414, 2011). "In addition to the known components of the hypercytokinemia response in influenza infection (IL6, IL29, CXCL10, CCL4) we have identified several other genes that our model can predict across species, which could be playing roles in initiating and/or sustaining this response." (PMID 22074594, 2011). "Induction of the proinflammatory cytokines IL-1β, IL-6, IL-8 and IFN-α mRNA levels were induced due to influenza H7N1 infection in the lungs of these chickens." (PMID 21314972, 2011). "Patients infected with highly pathogenic H5N1 have been shown to have higher levels of systemic IFNγ, IL-6, interferon-inducible protein of 10 kD (IP-10) and MCP-1 compared to individuals infected with human influenza subtypes." (PMID 21731666, 2011). "In this model, influenza-infected mice treated with Ekybion showed significant decreases in GCSF, GM-CSF, and IL-6." (PMID 20981272, 2011). "High levels of cytokines (e.g., IL-6, soluble tumor necrosis factor receptor 1) can be consistently found in CSF/blood specimens, correlating with disease severity and outcomes (hyperactivated cytokine response is absent in febrile seizure associated with influenza)." (PMID 20031062, 2010). "The concentrations of the cytokines IL-1β, IL-6, TNF-α, CXCL1,CXCL2, CCL5, IFN-γ and IL-12p40 were evaluated in lung homogenates ofcontrol and Influenza infected mice." (PMID 21079759, 2010). "In light of the ability of IL-6−/− mice to generate a comparable CD8+ T cell response to WT mice, influenza-specific CD4+ T cell responses were also assessed in both groups of mice." (PMID 18389078, 2008). "Although both WT and IL-6−/− mice elicited primary responses to influenza infection, the overall profile of CD4+ T cell infiltrating of the lung indicates that the T cell response was slightly delayed in IL-6−/− mice consistent with previous reports." (PMID 18389078, 2008). "Our study found that IL-6 levels were significantly increased after COVID-19 infection, but there were no significant changes in influenza patients." (PMID 40158620, 2026).
influenza (continued). "Given that JAK inhibition had the greatest effect on post‐influenza MRSA pneumonia, and IL‐6 activates the JAK/STAT pathway, we also investigated how deficiency of IL‐6 signaling might affect host susceptibility to post‐influenza bacterial pneumonia." (PMID 39921246, 2025). "A. paniculata may exert therapeutic effects against influenza by acting on core targets, such as TNF, IL‐6, AKT1, GAPDH, and STAT3." (PMID 41439108, 2025). "Decursin significantly reduces viral load in the lungs of influenza-infected models (>1 log), downregulates the ratio of p-PI3K/PI3K and p-Akt/Akt, and regulates the balance of IL-6, IL-17, TNF-α, and IL-10, effectively alleviating morphological abnormalities in lung tissue." (PMID 40860873, 2025). "Furthermore, and LNP-formulated influenza vaccine induced the stimulation and activation of antigen-specific CD4+ T follicular helper cells and germinal center B cells via IL-6 cytokine induction from lymph nodes." (PMID 40432140, 2025). "Less is known about the influence of influenza infections on iron metabolism, where this study identified FTH1 and FTL as top DEPs, but it could be reflective of macrophage and/or IL-6 responses." (PMID 41346583, 2025). "detected autoantibodies against antigens such as IL-6, IL-7, IL-12p70, and IL-22 in 48% of hospitalized patients with influenza, whereas none were found in the healthy control group." (PMID 40248710, 2025). "Using a mouse model of post‐influenza AF infection, including IL‐6 knockout mice, we found that IL‐6 signaling promotes neutrophilic lung inflammation but is not required for pathogen clearance of either influenza or AF." (PMID 40420617, 2025). "Together, these data suggest that the absence of IL‐6 does not impair host defense against post‐influenza bacterial super‐infection in the lung." (PMID 39921246, 2025). "Therefore, we sought to determine how inhibition of IL‐6 and JAK signaling affects both influenza infection and post‐influenza MRSA pneumonia." (PMID 39921246, 2025). "The absence of IL‐6 did not change bacterial burden in the lung during post‐influenza MRSA pneumonia." (PMID 39921246, 2025). "A. paniculata may exert its therapeutic effects against influenza by modulating core targets such as TNF, IL‐6, AKT1, GAPDH, and STAT3." (PMID 41439108, 2025). "To test whether this decreased neutrophil recruitment impairs the host ability to clear the invading pathogens, we investigated the burden of influenza and aspergillus during IAPA in IL‐6 knockout mice." (PMID 40420617, 2025). "IL-10 exerts anti-inflammatory effects in monocytes, and its elevation may suppress IL-6 and TNF-α production, contributing to the diminished immune response to influenza vaccination observed in older adults." (PMID 39591191, 2024). "Previous studies have shown that IL-6 levels are greater in children with IAE than in children with influenza without neurologic complications and that severity is positively correlated with inflammatory factor levels." (PMID 39624480, 2024). "At 7 dpi with influenza, BAL from mice exposed to e-cigarette aerosol generated from the carrier VG/PG or from VG/PG/Nic had significantly higher levels of IFN-γ, TNFα, IL-1β, IL-6, IL-17A, and MCP-1 compared to mice exposed to air." (PMID 36999019, 2023). "Here, we constructed influenza‐specific IgG landscapes and determined baseline concentrations of cytokines typically associated with chronic inflammation in older adults (TNF‐α, IL‐10, IL‐6, and IFN‐γ) in 30 high and 29 low influenza vaccine responders (HR and LR, respectively)." (PMID 37457646, 2023). "Exposure to aerosols generated from VG/PG with and without nicotine caused greater influenza-induced production in the distal airspaces of the pro-inflammatory cytokines IFN-γ, TNFα, IL-1β, IL-6, IL-17A, and MCP-1 at 7 days post inoculation (dpi)." (PMID 36999019, 2023). "Both IL6 and IL12 play important roles in the induction of immune responses against influenza." (PMID 36851183, 2023).
influenza (continued). "Likewise, influenza infection actively induces the cytokines’ expressions, like IL-6 and CXCL-10, and there is also a cell-autonomous relationship between influenza NS1 and Hh signaling." (PMID 35681469, 2022). "Recovery from influenza pneumonia can result in AM with increased surface MHC-II, and improved responses to subsequent bacterial infections including elevated induction of IL-6, which requires CCR2-mediated recruitment of monocytes that differentiate and replace the AM of embryonic origin." (PMID 35133985, 2022). "Regarding poly I:C, it was reported that the administration of poly I:C as an adjuvant in an H9N2 influenza vaccine significantly induced higher antibody titers and elevated expression levels of IFN-α, IFN-γ, IL-6, and major histocompatibility complex class II (MHC-II) in ducks." (PMID 35622731, 2022). "In fact, as Debisarun and colleagues highlight, influenza vaccinations modulate the responses against SARS-CoV-2, reducing IL-1β and IL-6 production while enhancing IL-1Ra release, and the cytokine storm due to dysregulated immune responses is well-known to underlie systemic SARS-CoV-2 damage." (PMID 35746506, 2022). "Furthermore, we found that ONP-302 reduced the levels of MPO, albumin, IL-6, and TNF-α in the lungs of aged, influenza-infected mice." (PMID 35737459, 2022). "It was noted that IL-6 was comparatively higher in those animals infected with a virus-carrying (A122) point alteration in NS1; hence, we hypothesize that past influenza pandemic was produced due to excessive production of cytokines storms (Hh dependent)." (PMID 35681469, 2022). "We further found that IL-6, unlike neutrophils, was required to generate normal Tfh cells and antibody responses, but not for protection from influenza challenge." (PMID 35073387, 2022). "In addition to examining IL-6 alone, we looked at the combination of IL-6 and serum C-reactive protein (CRP) to assess influenza severity." (PMID 34692664, 2021). "By day 7, expression of Ccl3, Cxcl9, Cd86, Il-6, Cd80, and Cxcl11 remained elevated in young adult lung in response to H1N1, while expression of Ccl5, Ccl4, and Cd40 remained elevated in response to either strain of influenza." (PMID 34829979, 2021). "Cytokines such as IL-4, IL-5, IL-6, IL-8, IL-13, and TNF-α, chemokines such as CCL2 and CCL3, and the MC proteases tryptase and chymase can be detected in the supernatants of influenza infected MC cultures and in the bronchioalveolar lavage fluid (BALF) of both influenza patients and infected mice." (PMID 33680987, 2021). "Moreover, influenza vaccination modulated the responses against SARS-CoV-2, reducing IL-1β and IL-6 production while enhancing IL-1Ra release." (PMID 34695164, 2021). "In addition, hsa-miR-326, hsa-miR-15b-5p, hsa-miR-885, hsa-miR-122-5p, hsa-miR-133a-3p, and hsa-miR-150-5p showed high correlations to IL-6, IL-15, IL-17A, IL-1β, and monocyte chemoattractant protein-1 (MCP-1) with both strains of influenza." (PMID 33540650, 2021). "Likewise, bafilomycin A1, erythromycin, and clarithromycin were studied to impede the making of IL-1β, IL-6, IL-8, TNF-α, and intercellular adhesion molecule (ICAM)-1 in influenza and rhinovirus-modeled infections." (PMID 33937285, 2021). "Although the limit of detection of the IL-6 test strip system is not as sensitive as the ELISA used in this study (3.1 pg/ml), it is sufficient to distinguish between the mild and severe influenza cases in children." (PMID 34692664, 2021). "Furthermore, activation of PAR-1 triggers IL-6 and CXCL1/KC release and increases lung inflammation in mice after influenza infection." (PMID 34658893, 2021). "However, it was shown that this fragment enhanced influenza infection as well as expression of inflammatory cytokines TNF-α, IFN-α, IFN-β, IL-12, IL-6, and RANTES, contrasting to the native molecule." (PMID 33542724, 2020).
influenza (continued). "Although the previous reports of use of IL-6 blockers to treat CRS have shown mixed results, recent clinical data for α-IL-6 and α-IL-6R mAbs have shown early promise in human trials for treatment of severe influenza and corona virus infections." (PMID 33071786, 2020). "While intramuscular immunization does not protect against lethal challenge, intranasal administration of heat inactivated virus is protective and correlates with expression of IL-6 in the lung, activation of lung CD8 cells, and development of an influenza-specific antibody response." (PMID 33193346, 2020). "At the same time, the previous experiments confirmed that neutralization of IL-6 alone did not have a positive effect on the respiratory bacterial burden in secondary pneumococcal infection following influenza infection." (PMID 31474978, 2019). "Interestingly, this module contains IL-6, IL-8, and MCP-1, which have been previously reported to be hyperactivated in subjects with severe influenza infection." (PMID 31275311, 2019). "In line with this view, hippocampal elevations of IL-1β in a mouse model of influenza were limited in mice that had been housed in an EE, whereas IL-6 increases in influenza-exposed mice were not influenced by enrichment." (PMID 30065637, 2018). "In addition, IFN-λ increases influenza-induced Th1 cytokines (IFN-γ, IL6), whereas influenza-induced Th2 cytokines decrease (IL4, IL5, IL9, IL13)." (PMID 28293236, 2017). "In A549 cells we found that treatment with calcitriol prior to and post infection with H9N2 influenza significantly decreased the mRNA expression levels of IL-6, IFN-β and the viral M gene compared to infected cells not treated with calcitriol." (PMID 28114957, 2017). "In addition, our recent study demonstrated that there are lingering inflammatory cytokines such as IL-6, IL-1α, and G-CSF in the bronchiolar lavage fluid (BAL) of aged mice during influenza infection." (PMID 28979265, 2017). "Calcitriol treatment prior to and post infection with H9N2 influenza significantly decreased expression of the influenza M gene, IL-6, and IFN-β in A549 cells, but did not affect virus replication." (PMID 28114957, 2017). "Considering these findings together with the previous observation of elevated levels of the pro-inflammatory cytokines IL-12, IL-6, and IFN-γ in severe influenza patients, it is likely that cytokines drive these memory-like responses during influenza infections." (PMID 28955346, 2017). "Significant increases in the expression levels of the M gene, IL-6 and IFN-β were observed in A549 cells infected with H9N2 influenza compared with uninfected control cells, indicating that hyperinflammatory responses were elicited by H9N2 influenza virus infection." (PMID 28114957, 2017). "Indeed, we found that influenza infection strongly induced CXCL-10 and IL6 expression, the latter of which was partially enabled by a direct interaction between Hh signaling and NS1." (PMID 28837667, 2017). "Similarly, influenza infection strongly induced expression of cytokines CXCL-10 and IL6, the latter at least partially by a direct, cell-autonomous interaction between Hh signaling and NS1." (PMID 29214147, 2017). "We detected both a cell-autonomous effect of influenza inducing an increase in IL6 expression in infected cells, as well as a general non-autonomous increase in mouse lung tissue." (PMID 28837667, 2017). "In addition to morbidity, both IL-6 and TNF-α levels positively correlated with influenza viral burden." (PMID 24324838, 2013). "To determine the possible impact of ST2 on pulmonary inflammation during influenza infection, we measured lung levels of cytokines (IFN-γ, TNF-α, IL-1β, IL-6, IL-10, IL-33, IL-13, IL-5) and chemokines (KC, MIP-2) at 3, 8 and 14 days following influenza inoculation." (PMID 23483993, 2013). "In addition to IL-6, human serum studies identified TNF-α to be positively correlated with influenza severity." (PMID 24324838, 2013).